PHF2 (PHD finger protein 2)
Description:
Lysine demethylase that demethylates both histones and non-histone proteins. Enzymatically inactive by itself, and becomes active following phosphorylation by PKA: forms a complex with ARID5B and mediates demethylation of methylated ARID5B. Demethylation of ARID5B leads to target the PHF2-ARID5B complex to target promoters, where PHF2 mediates demethylation of dimethylated 'Lys-9' of histone H3 (H3K9me2), followed by transcription activation of target genes. The PHF2-ARID5B complex acts as a coactivator of HNF4A in liver. PHF2 is recruited to trimethylated 'Lys-4' of histone H3 (H3K4me3) at rDNA promoters and promotes expression of rDNA. Involved in the activation of toll-like receptor 4 (TLR4)-target inflammatory genes in macrophages by catalyzing the demethylation of trimethylated histone H4 lysine 20 (H4K20me3) at the gene promoters (By similarity).
Synonyms: CENP-35; KIAA0662; JHDM1E; KDM7C; GRC5
Tractability: Small molecule: a structure with a bound ligand is known; it has a binding pocket of medium quality. PROTAC: UniProt records ubiquitination sites on it; ubiquitination databases record sites on it; its protein half-life has been measured.
Target class: Enzyme; Oxidoreductase
Gene: Protein-coding gene on chromosome 9 (93,576,584 to 93,679,599, forward strand). Ensembl gene ENSG00000197724.
Subcellular location: Nucleus, nucleolus; Chromosome, centromere, kinetochore
Subcellular location (Human Protein Atlas): Nucleoli rim; Nucleoplasm
Pathways (Reactome):
Chromatin organization: HDMs demethylate histones
Gene Ontology:
Molecular function: histone H3K4me3 reader activity; histone H3K9 demethylase activity; iron ion binding; protein binding; transcription coactivator activity; zinc ion binding; histone demethylase activity; histone H4K20 demethylase activity; transcription coregulator activity
Biological process: negative regulation of rDNA heterochromatin formation; protein demethylation; transcription initiation-coupled chromatin remodeling; chromatin remodeling; liver development; regulation of transcription by RNA polymerase II; positive regulation of DNA-templated transcription
Cellular component: catalytic complex; kinetochore; nucleolus; nucleoplasm; nucleus
Genetic constraint (gnomAD): Loss-of-function variants: 25 observed, 106.27 expected, observed/expected ratio (o/e) 0.24, 90% interval 0.17 to 0.33. The upper end of that interval is the gene's LOEUF score, 0.33, which puts it in group 1 of 6, group 1 being the genes least tolerant of losing a copy. Missense variants: 993 observed, 1,355.6 expected, observed/expected ratio (o/e) 0.73, 90% interval 0.69 to 0.77. Synonymous variants: 548 observed, 565.22 expected, observed/expected ratio (o/e) 0.97, 90% interval 0.9 to 1.04.
Homologues: Orthologues: macaque PHF2 (99% identical), chimpanzee PHF2 (98% identical), rat Phf2 (94% identical), mouse Phf2 (94% identical), pig PHF2 (93% identical), dog PHF2 (91% identical), guinea pig PHF2 (90% identical), rabbit PHF2 (82% identical), tropical clawed frog phf2 (74% identical), zebrafish phf2 (67% identical), Drosophila melanogaster Kdm2 (24% identical), Caenorhabditis elegans jhdm-1 (19% identical), and 2 more. Paralogues in human: PHF8 (46% identical), KDM7A (34% identical), KDM2B (21% identical), KDM2A (18% identical).
Diseases named in the same sentence as PHF2 in open-access papers:
PHF2 is named in the same sentence as 52 diseases in open-access papers, as found by Europe PMC text mining. Sharing a sentence is not in itself a finding about the gene and the disease. The quoted sentences say what the papers report.
breast carcinoma (8 papers, 2008 to 2025). "This regulatory mechanism underlines PHF2’s role in maintaining the epithelial state of breast cancer cells, thereby countering metastatic behaviors and tumor progression." (PMID 38813086, 2024). "The role of PHF2 in cancer is controversial since its expression is increased in oesophageal and renal carcinoma, but the PHF2 gene is mutated in gastric and colorectal cancer as well as deleted or hypermethylated at the promotor region in breast cancer." (PMID 40082888, 2025). "In ovarian and breast cancers, PHF2 counteracts oncogenesis by promoting tumor suppressor gene transcription, disrupting EMT." (PMID 38813086, 2024). "Deregulation of PHF2 has been linked with various malignancies, such as renal cell carcinoma and breast cancer, as abnormal PHF2 activity disrupts the expression of oncogenes and tumor suppressor genes, facilitating tumor growth and progression." (PMID 39765675, 2024). "PHF2 is downregulated in breast cancer, and overexpression of PHF2 has been shown to inhibit the proliferation of breast cancer cells." (PMID 37828054, 2023). "In breast cancer, alterations in the PHF2 gene were observed in up to 60% of patients and reduction in the PHF2 mRNA expression was identified." (PMID 29416602, 2018). "Similarly, PHF2 inhibits cancer progression in breast cancer by stimulating the transcription of tumor suppressor genes such as E-cadherin and PHF2 itself, in concert with FOXA2." (PMID 38813086, 2024). "In addition to lung cancer, TCGA database also revealed significantly reduced PHF2 levels in various primary tumors, such as breast cancer (BRCA) and kidney renal papillary cell carcinoma (KIRP)." (PMID 36872368, 2023). "In this study, we found that FOXP2 could bind to certain promoters and stimulate the transcription of its target genes such as PHF2 and E-cadherin in breast cancer cells." (PMID 33718155, 2021). "Together, the results suggested that FOXP2 could inhibit EMT in breast cancer cells by activating transcription of certain genes, such as E-cadherin and PHF2." (PMID 33718155, 2021). "PHF2 was considered as a tumor suppressor because of its decreased levels in various tumor tissues and could up-regulate certain epithelial genes, leading breast cancer cells to acquire epithelial phenotypes." (PMID 33718155, 2021). "Deletion analysis of PHF2, FANCC, PTCH1 and XPA were examined in a subset of 47 early-onset (group-A: ≤ 40 years) and 59 late-onset (group-B: > 40 years) breast carcinomas using both microsatellite and exonic markers." (PMID 18990233, 2008). "Together, the results suggested that FOXP2 could inhibit EMT by activating the transcription of certain genes, such as E-cadherin and PHF2, in concert with FOXA2 in breast cancer cells." (PMID 33718155, 2021).
hepatocellular carcinoma (5 papers, 2019 to 2026). A malignant tumor that arises from hepatocytes. "miR-221 can target PHF2, and its upregulation along with PHF2 decrease has been shown in hepatocellular carcinoma cells." (PMID 35087589, 2022). "Levels of miR-221 and plant homeodomain finger 2 (PHF2) expressions in human hepatocellular carcinoma (HCC) tissues and cell lines were detected using western blotting and quantitative real-time PCR (qRT-PCR)." (PMID 31214616, 2019). "Notably, SREBP1c increases free fatty acids in hepatocellular carcinoma (HCC) cells, and the consequent PA induction triggers the PHF2/SREBP1c axis." (PMID 37828054, 2023).
Anxiety (3 papers, 2021 to 2023). Intense feelings of nervousness, tension, or panic often arise in response to interpersonal stresses. "Interestingly, the largest GWAS study identified six genetic susceptibility loci that were significantly associated with IBS, four of which were located in genes associated with mood and anxiety (NCAM1, CADM2, PHF2/FAM120A, DOCK9)." (PMID 36071849, 2022).
colon cancer (2 papers, 2018 to 2023). "Alterations in PHF2 have been identified in several cancer types, including breast, oesophageal, stomach and colon cancer." (PMID 29416602, 2018). "For colon cancer, PHF2 expression was decreased in cancer tissue and the Oncomine database revealed PHF2 down-regulation in colon and stomach cancers." (PMID 29416602, 2018).
esophageal squamous cell carcinoma (2 papers, 2019 to 2022). Esophageal squamous cell carcinoma (ESCC) is a type of esophageal carcinoma (EC) that can affect any part of the esophagus, but is usually located in the upper or middle third. "Meanwhile, PHF2 are overexpressed in esophageal squamous cell carcinoma (ESCC) and was associated with decreased overall survival of ESCC patients." (PMID 31214616, 2019). "The overexpression of PHF2 in esophageal squamous cell carcinoma (ESCC) is correlated to decreased overall survival rate of ESCC patients." (PMID 35729160, 2022).
Hepatic steatosis (2 papers, 2018 to 2021). Steatosis is a term used to denote lipid accumulation within hepatocytes. "The histone demethylase plant homeodomain finger 2 (Phf2) was recently shown to induce hepatic steatosis through the upregulation of carbohydrate-responsive element-binding protein (ChREBP) target genes." (PMID 34681759, 2021). "Overall, these results demonstrate that enhanced Nrf2 activity is determinant to prevent the progression into fibrosis in the context of Phf2-induced hepatic steatosis development." (PMID 29844386, 2018). "Overall, Phf2 overexpression by controlling metabolic rerouting and lipid sequestration favors hepatic steatosis development as revealed by increased liver triglyceride (TG), diacylglycerol (DAG), and cholesterol ester contents." (PMID 29844386, 2018). "Phf2 overexpression led to hepatic steatosis development as shown by increased liver weight and by oil red O staining of liver sections." (PMID 29844386, 2018). "In this study, we identify the histone demethylase plant homeodomain finger two (Phf2), which belongs to the KDM7 histone demethylase family, as a component of the ChREBP-assembled transcriptional complex, a transcription factor previously implicated in hepatic steatosis development." (PMID 29844386, 2018). "Altogether, our results suggest that Phf2-mediated SFA desaturation into DAG and TG protects the liver from inflammation and insulin resistance despite hepatic steatosis development." (PMID 29844386, 2018).
Hyperglycemia (2 papers, 2018 to 2019). An increased concentration of glucose in the blood. "Interestingly, specific co-recruitment of Phf2 and ChREBP to the promoter of nuclear factor erythroid 2 like 2 (Nrf2) contributes to the protective effect of Phf2 against increased reactive oxygen species (ROS) and NAFLD progression in the context of hyperglycemia." (PMID 31275349, 2019). "In addition, Phf2 mice did not develop fasting hyperglycemia and fasting hyperinsulinemia as compared to HFHSD-GFP mice." (PMID 29844386, 2018).
Insulin resistance (2 papers, 2018 to 2021). Increased resistance towards insulin, that is, diminished effectiveness of insulin in reducing blood glucose levels. "As a consequence, Phf2 activation protects the liver from inflammation, oxidative stress, insulin resistance, and fibrosis development during the pathogenesis progression of NAFLD during obesity." (PMID 29844386, 2018). "Overall, as lipotoxicity is generally attributed to SFAs, their conversion into specific MUFAs could be instrumental in the protective effect of Phf2 from inflammation and insulin resistance, by decreasing their intracellular concentrations." (PMID 29844386, 2018). "As a result, Phf2 overexpression, although increasing both DAG and TG content, protected hepatocytes from palmitate-induced insulin resistance and inflammation." (PMID 29844386, 2018). "However, despite an active pro-fibrogenic response due to impaired anti-oxidant capacities, Nrf2 KO mice overexpressing Phf2 did not developed insulin-resistance as a result of enhanced oxidative stress." (PMID 29844386, 2018). "By specifically erasing H3K9me2 methyl-marks on the promoter of ChREBP-regulated genes, Phf2 facilitates incorporation of metabolic precursors into mono-unsaturated fatty acids, leading to hepatosteatosis development in the absence of inflammation and insulin resistance." (PMID 29844386, 2018).
lymph node metastasis (2 papers, 2019 to 2023). "Furthermore, the protein level of PHF2 was also correlated with lymph node metastasis-pN status, depth of invasion and serum AFP (P < 0.05, paired χ2 test)." (PMID 31214616, 2019). "Meanwhile, the protein level of PHF2 was correlated with depth of invasion, TNM stage and lymph node metastasis-pN status." (PMID 31214616, 2019).
Obesity (2 papers, 2018). Accumulation of substantial excess body fat. "Compared to GFP, Phf2 mice were fully protected from HFHSD-induced obesity, despite the fact that detailed analysis of food intake, using lean body mass as a covariate, revealed that they were hyperphagic on both NCD and HFHSD." (PMID 29844386, 2018). "However, the regulation of Phf2 activity in hepatocytes and its contribution to the physiopathology of obesity and type 2 diabetes and more specifically to the development and/or progression of NAFLD are currently unknown." (PMID 29844386, 2018). "Consequently, to determine whether Phf2 activation could protect liver from fibrosis development during obesity, Phf2 (FLAG-tagged) was stably overexpressed specifically in the liver, through a similar AAV strategy." (PMID 29844386, 2018). "Moreover, the Phf2-mediated activation of the transcription factor NF-E2-related factor 2 (Nrf2) further reroutes glucose fluxes toward the pentose phosphate pathway and glutathione biosynthesis, protecting the liver from oxidative stress and fibrogenesis in response to diet-induced obesity." (PMID 29844386, 2018).
steatosis (2 papers, 2018 to 2019). Increased lipid within the cytoplasm of cells. "Phf2-overexpressing mice develop steatosis, and Arid5b knockout mice are resistant to high fat diet-induced weight gain and obesity." (PMID 31882756, 2019). "Taking into account Phf2 expression and activity as a reliable biomarker, our study could also lead to disease stratification, from simple steatosis to NASH and fibrosis, providing new tracks in NAFLD pathogenesis." (PMID 29844386, 2018).
stomach cancers (2 papers, 2018 to 2019). "Moreover, a colon and stomach cancer tissue study showed that PHF2 is positively correlated with p21 expression." (PMID 29416602, 2018).
acute lymphoblastic leukemia (1 paper, 2020). Leukemia with an acute onset, characterized by the presence of lymphoblasts in the bone marrow and the peripheral blood. "The expression of PHF2 is markedly reduced in various subsets of acute lymphoblastic leukemia (ALL) patients." (PMID 32085659, 2020).
Alzheimer disease (1 paper, 2026). A progressive, neurodegenerative disease characterized by loss of function and death of nerve cells in several areas of the brain leading to loss of cognitive function such as memory and language. "The present study has identified PHF2 as a promising player regulating inflammation genes and ensuing biological processes in Alzheimer’s disease." (PMID 40849543, 2026).
and neck cancers (1 paper, 2021). "Its abnormal expression in breast, head, and neck cancers suggests the potential function of PHF2 as a tumor suppressor." (PMID 34329293, 2021).
cognitive decline (1 paper, 2026). "The connection between PHF2 activity and neuroinflammatory gene expression suggests that PHF2 could be a pivotal factor in the neuroinflammatory processes that contribute to neuronal damage and cognitive decline in AD." (PMID 40849543, 2026).
Ewing sarcoma (1 paper, 2020). A small round cell tumor that lacks morphologic, immunohistochemical, and electron microscopic evidence of neuroectodermal differentiation. "Further, examination of public, outcome-annotated, patient tumor gene expression data showed higher PHF2 expression levels to significantly associate with more aggressive Ewing sarcoma disease." (PMID 33196691, 2020). "PHF2 demethylase activity, directed at repressive H3K9 and H3K27 histone methyl marks, is likely to be responsible for PHF2-dependent gene expression in Ewing sarcoma, although this remains to be determined." (PMID 33196691, 2020). "In the present study, we present evidence that epigenetic mechanisms, involving the chromatin factors KDM5A and PHF2, importantly contribute to Ewing sarcoma progression, in part through their opposing effects on EWS/Fli1-controlled gene expression." (PMID 33196691, 2020). "To probe the functional roles of KDM5A and PHF2 in Ewing sarcoma, we stably depleted each factor in patient-derived Ewing sarcoma cell lines, using lentivirally delivered shRNAs." (PMID 33196691, 2020). "Together, these studies identify KDM5A and PHF2 as novel disease-promoting factors, and potential new targets, in Ewing sarcoma, including the more metastatically potent EWS/Fli1low cell population." (PMID 33196691, 2020). "Similar to PHF2, higher L1CAM expression is significantly associated with inferior clinical outcome in Ewing sarcoma." (PMID 33196691, 2020). "Here, we show that the epigenetic regulators KDM5A and PHF2 promote growth and metastatic properties in Ewing sarcoma, and, strikingly, activate expression many pro-metastatic genes repressed by EWS/Fli1." (PMID 33196691, 2020). "Together, these data indicate that KDM5A and PHF2 each promote growth and metastatic properties in Ewing sarcoma." (PMID 33196691, 2020). "Together, these data suggested that KDM5A and PHF2 could be novel disease-promoting factors in Ewing sarcoma." (PMID 33196691, 2020). "Seeking to further understand the biology of JHDMs in Ewing sarcoma, we noted the JHDMs KDM5A (JARID1A/RBBP2) and PHF2 (KDM7C/JHDM1E) to be consistently upregulated in expression in patient-derived Ewing sarcoma cell lines, relative to mesenchymal stem cells, the putative disease cell of origin." (PMID 33196691, 2020). "Stable depletion of KDM5A and PHF2 each resulted in inhibition of colony formation, indicating that both factors exert growth-promoting effects in Ewing sarcoma." (PMID 33196691, 2020). "To obtain further insight into mechanisms by which KDM5A and PHF2 function as disease promoting factors in Ewing sarcoma, we defined their respective transcriptomes using RNAseq, comparing gene expression in A673 Ewing sarcoma cells stably depleted of each factor and shRNA control cells." (PMID 33196691, 2020). "Having shown that KDM5A and PHF2 promote metastatic properties in Ewing sarcoma, and exert effects on metastasis in opposition to those of EWS/Fli1, we wondered whether inhibition of KDM5A or/and PHF2 could impair the biological properties of more metastatically potent EWS/Fli1low cells." (PMID 33196691, 2020). "Examination of regulatory control of MCAM in different Ewing sarcoma cell lines revealed positive regulation by KDM5A in both A673 and SK-ES-1 cells, and by PHF2 in A673 cells." (PMID 33196691, 2020). "Our studies further identify a group of genes previously implicated in metastasis, whose opposing regulatory control by KDM5A/PHF2 and EWS/Fli1 may importantly contribute to modulation of Ewing sarcoma metastatic potency." (PMID 33196691, 2020). "Inspection of individual genes of interest revealed that KDM5A and PHF2 each positively control the expression of Ets1 and MCAM, genes belonging to a metastasis-promoting pathway recently identified in Ewing sarcoma by our group, and negatively regulated by EWS/Fli1." (PMID 33196691, 2020).
Glucose intolerance (1 paper, 2021). Glucose intolerance (GI) can be defined as dysglycemia that comprises both prediabetes and diabetes. "Overexpression of PHF2 in mice led to improved glucose intolerance and IR and reduced expression of proinflammatory genes." (PMID 35087408, 2021).